MT1B (metallothionein 1B)
Description:
Metallothioneins have a high content of cysteine residues that bind various heavy metals; these proteins are transcriptionally regulated by both heavy metals and glucocorticoids.
Synonyms: MT-1B; MT-IB; MT1Q; MT1; MTP
Tractability: No criterion of Open Targets' tractability assessment is met for any kind of drug.
Gene: Protein-coding gene on chromosome 16 (56,651,886 to 56,653,204, forward strand). Ensembl gene ENSG00000169688.
Pathways (Reactome):
Cellular responses to stimuli: Metallothioneins bind metals
Gene Ontology:
Molecular function: protein binding; metal ion binding; zinc ion binding
Biological process: cellular response to zinc ion; cellular response to cadmium ion; cellular response to copper ion; detoxification of copper ion; intracellular zinc ion homeostasis; negative regulation of growth
Cellular component: cytoplasm; nucleus
Genetic constraint (gnomAD): Loss-of-function variants: 5 observed, 10.23 expected, observed/expected ratio (o/e) 0.49, 90% interval 0.25 to 1.03. The upper end of that interval is the gene's LOEUF score, 1.03, which puts it in group 4 of 6, group 1 being the genes least tolerant of losing a copy. Missense variants: 76 observed, 78.71 expected, observed/expected ratio (o/e) 0.97, 90% interval 0.8 to 1.17. Synonymous variants: 22 observed, 29.4 expected, observed/expected ratio (o/e) 0.75, 90% interval 0.53 to 1.07.
Homologues: Orthologues: chimpanzee MT1B (98% identical), zebrafish mt2 (61% identical). Paralogues in human: MT1H (87% identical), MT1X (87% identical), MT1A (85% identical), MT1F (85% identical), MT1G (85% identical), MT1M (85% identical), MT2A (85% identical), MT1HL1 (84% identical), MT3 (70% identical), MT4 (59% identical), MT1E (52% identical).
Diseases named in the same sentence as MT1B in open-access papers:
MT1B is named in the same sentence as 23 diseases in open-access papers, as found by Europe PMC text mining. Sharing a sentence is not in itself a finding about the gene and the disease. The quoted sentences say what the papers report.
colorectal cancer (4 papers, 2019 to 2024). A primary or metastatic malignant neoplasm that affects the colon or rectum. "MT1B has been reported to be down-regulated in colorectal cancer and is associated with poor clinical outcome; however, this gene is up-regulated in other cancers, such as non-small cell lung cancer." (PMID 37889013, 2023). "When colorectal cancer occurs, the levels of MT1B, MT1F, and MT1G genes are down-regulated, and MT genes may be able to serve as effective markers for the diagnosis of the disease." (PMID 39061894, 2024). "In addition, high expression levels of the MT1B, MT1H, and MT1L genes are associated with a good prognosis in colorectal cancer patients and can predict the prognosis of the disease." (PMID 39061894, 2024). "Collectively, these results indicate that high expression of MT1B, MT1H, or MT1L correlates with good prognosis in colorectal cancer patients." (PMID 31394742, 2019).
lung carcinoma (3 papers, 2021 to 2023). "The authors found MT-1A C/A, MT-1B G/A and MT-1F C/T variants to significantly increase the risk of lung cancer." (PMID 36981043, 2023). "Hence, the upregulation of MT1B, MT1F, MT1G, and MT1H in HPAEpiCs after exposure to PHMG may be involved in the development of lung cancer." (PMID 34564354, 2021).
liver diseases (2 papers, 2024 to 2025). "Recent studies have indicated that the expression changes of MT1B are closely associated with the progression of various liver diseases." (PMID 39551239, 2024).
breast carcinoma (1 paper, 2011). "The mRNA of MT-1 series named as A, E, F, G, H, X and MT-3 isoforms but not MT-1B and MT-4 isoforms have been detected in breast cancer tissues." (PMID 21599891, 2011).
gastric cancer (1 paper, 2019). A primary or metastatic malignant neoplasm involving the stomach. "Notably, DNA methylation of some MT isoforms in gastric cancer, like MT1A, MT1B, MT1H, MT1M, MT3, and MT4, was higher than their paired normal tissue except remaining isoforms." (PMID 31380415, 2019).
lipid metabolic disorders (1 paper, 2024). "The results showed that the exacerbation of lipid metabolic disorders caused by MT1B silencing in HepG2 and AML12 cells could be rescued by treatment with AKT inhibitor." (PMID 39551239, 2024). "Rescue experiments in vitro and in vivo confirmed that Zn ion treatment alleviate HFD-induced lipid metabolic disorders and inhibit the expression of inflammatory factors, but these effects were reversed by Mt1b silencing." (PMID 39551239, 2024). "Further rescue experiments confirmed that Zn2+ could alleviate high-fat–induced lipid metabolic disorders, inhibit the activation of AKT/PI3K pathway and the expression of inflammatory factors in vitro and in vivo, but these effects were reversed by Mt1b silencing." (PMID 39551239, 2024).
liver fibrosis (1 paper, 2024). "In vivo, specific downregulation of Mt1b in mouse liver significantly increased TG and TC levels and lipid accumulation, aggravated liver fibrosis, and upregulated proinflammatory factors, along with an increase in p-AKT expression." (PMID 39551239, 2024). "Furthermore, reduced Mt1b expression aggravated liver fibrosis and led to the upregulation of proinflammatory factors in the liver." (PMID 39551239, 2024).
type 2 diabetes (1 paper, 2009). "Melatonin receptor 1B (MT1B), AIS, glucose metabolism and type 2 diabetes." (PMID 19878575, 2009).
tumor (3 papers, 2013 to 2019). "Apart from MT1B, MT1F, and MT4, other MT isoforms in tumor tissue were both downregulated significantly in Oncomine and GEPIA databases." (PMID 31380415, 2019).
cancer (2 papers, 2023). A tumor composed of atypical neoplastic, often pleomorphic cells that invade other tissues. "MT1B, known as an important isoform of metallothioneins (MTs), was reported to participate in the regulation of copper-zinc homeostasis, and MTs play an important role in tumorigenesis, angiogenesis, metastasis, proliferation and immunomodulation of cancers." (PMID 37862114, 2023).
liver (1 paper, 2024). "In vivo experiments demonstrate that specific downregulation of hepatic MT1B expression via AAV8-shMT1B injection significantly increases triglyceride and total cholesterol levels, exacerbates lipid accumulation, and markedly elevates liver fibrosis and inflammatory factor expression." (PMID 39551239, 2024).
metabolic disease (1 paper, 2024). A congenital disorder (due to inherited enzyme abnormality) or acquired (due to failure of a metabolically important organ) disorder resulting from an abnormal metabolic process. "Further experiments indicate that AKT inhibition can reverse the lipid metabolism disorders and inflammatory responses caused by MT1B downregulation." (PMID 39551239, 2024). "Future research will focus on further exploring the biological functions of MT1B and its potential applications in other metabolic diseases, aiming to achieve breakthroughs in the diagnosis and treatment of related diseases." (PMID 39551239, 2024).
MT1B also shares sentences with these, for which no sentence is quoted: periodontal disease (2 papers); amyloidosis (1); Cirrhosis (1); colon cancer (1); colorectal tumor (1); Down syndrome (1); Hepatic steatosis (1); hepatocellular carcinoma (1); metabolic dysfunction-associated steatohepatitis (1); metabolic dysfunction-associated steatotic liver disease (1); non-small cell lung carcinoma (1).